Y_RNA (Y RNA )
Gene: Miscellaneous RNA gene on chromosome 12 (122,768,099 to 122,768,200, forward strand). Ensembl gene ENSG00000206914.
Homologues: Orthologues: chimpanzee Y_RNA (99% identical), macaque Y_RNA (92% identical). Paralogues in human: Y_RNA (91% identical), RNY3 (90% identical), Y_RNA (90% identical), RNY3P1 (89% identical), Y_RNA (89% identical), Y_RNA (88% identical), RNY3P14 (87% identical), Y_RNA (87% identical), Y_RNA (86% identical), RNY3P5 (85% identical), Y_RNA (85% identical), RNY3P11 (84% identical), and 98 more.